CXCR2 (C-X-C motif chemokine receptor 2)
Diseases named in the same sentence as CXCR2 in open-access papers (continued):
Sharing a sentence is not in itself a finding about the gene and the disease.
tumor (continued). "On the other hand, a reduction of CXCR2 expression in tumor cells led to the inhibition of tumor growth and development of incomplete VM structures in the animal GBM models." (PMID 32456359, 2020). "Treatment of tumor-bearing mice with the CXCR2 inhibitor SX-682 and anti-CXCR2 antibodies decreased the migration of MDSCs, suppressed the tumor-promoting response, and improved the efficacy of anti-PD1 therapy." (PMID 32942545, 2020). "Our initial studies confirmed the increased expression of CXCL8 and its two receptors CXCR1 and CXCR2 in the tumour epithelium of human CaP." (PMID 32743555, 2020). "Inhibition of CXCR2 decreased tumor growth and angiogenesis in a genetic murine model of pancreatic ductal adenocarcinoma." (PMID 31690961, 2020). "The diagnostic specificity for CXCR4 levels (69%) was higher than that for CXCR2 (66%) and the classical tumor marker (CEA–47%), but lower in comparison to CRP levels (94%), similarly to the predictive value for positive (PV+ve) results." (PMID 32867211, 2020). "Neutrophils expressing CXCR2 on their surface sense the chemotactic gradient move toward the higher concentration of CXCR2 ligands and get in direct contact with the tumor." (PMID 32411122, 2020). "These chemokines interact with the promiscuous chemokine receptor, CXCR2, expressed on neutrophils, as well as on many types of tumor cells, to initiate the influx of pro-tumoral neutrophils of the MDSC phenotype, while IL-8 interacts selectively with CXCR1." (PMID 32244751, 2020). "CXCR2 was involved in the tumor growth and stemness maintenance in ccRCC, and chemoresistance, tumor metastasis and angiogenesis in other cancers." (PMID 33324547, 2020). "Triple combination of a CSF-1R inhibitor, a CXCR2 antagonist, and anti-PD-1 antibody lead to a significant inhibition of tumor growth in several cancer mouse models." (PMID 32509781, 2020). "Pharmacological inhibition of CXCR1 or CXCR2 represses neutrophil infiltration into tumor sites, thus resulting in repression of tumor growth." (PMID 32296583, 2020). "The CXCR1 and CXCR2 inhibitor SX-682 has already proven to promote tumor clearance following adoptive cell transfer of tumor antigen specific T cells in mouse models of squamous cell carcinomas." (PMID 34458892, 2020). "SX-682 is an orally available allosteric inhibitor of CXCR1 and CXCR2 that has shown promise in promoting tumor regression pre-clinically." (PMID 34458892, 2020). "Cxcr2 was also analyzed, given that it plays a role in the tumor microenvironment by recruiting neutrophils to inflammatory sites." (PMID 32244885, 2020). "Changes in the RNA levels of chemokine receptors were consistent with this maturation defect, with bone-marrow derived neutrophils from tumor-bearing castrated mice characterized by decreased CXCR2 and increased CXCR4 and VLA4." (PMID 32235862, 2020). "Mutated KRAS gene (KRASG12D)-mediated suppression of IRF2 in colorectal cancer leads to increased secretion of CXCL3, thereby promoting the migration of MDSCs into tumor sites through interaction with CXCR2." (PMID 32942545, 2020). "Collectively, our data suggest FMNL1 serve as a promising prognostic factor in ccRCC and function as an oncogene to promote tumor metastasis through upregulation of CXCR2." (PMID 33324547, 2020). "By targeting CXCR2, MDSCs were diminished to block tumor metastasis, promoting T‐cell infiltration into the tumors and extending survival in pancreatic cancer." (PMID 33613512, 2020). "Myeloid-derived suppressor cells (MDSC) expressing CXCR2 can be recruited to the developing tumor by CXCL1 and CXCL2, possibly induced by PGE2." (PMID 32276475, 2020). "To further ensure that IL-8 contributes to the recruitment of neutrophils into the tumour microenvironment, we applied the CXCR2 small molecule inhibitor SB225002 to subcutaneously transplanted EOC model." (PMID 32778818, 2020).
tumor (continued). "Recent observations have shown that the chemokine CXCL1 and its receptor CXCR2 assist with the homing of neutrophils into the tumor microenvironment." (PMID 32079335, 2020). "CXCR1 and CXCR2 are kinds of G protein–coupled receptors, and activation of receptors can contribute to many actions including angiogenesis and tumour growth." (PMID 32588946, 2020). "The cellular endpoint effects induced by the IL-8 CXCR1/CXCR2 axis, in normal epithelial cells, tumor cells or other cells in the tumor microenvironment, promote cellular survival, proliferation, angiogenesis, and a stem cell phenotype." (PMID 32793466, 2020). "First, CXCR2 signalling has been shown to play a role in the modulation of the tumour immune microenvironment and the recruitment of MDSCs in distant metastatic sites, along with the consequent development of the pre-metastatic niche." (PMID 32581213, 2020). "Chemokine CXCL1 is a monomeric protein of chemotaxis cytokines, which specifically binds to its receptor CXCR2 and has been reported to promote tumor growth and metastasis in various cancers." (PMID 33223508, 2020). "In colorectal cancer, KRASG12D-mediated suppression of IRF2 results in high expression of CXCL3, which binds to CXCR2 on MDSCs and promotes their recruitment into tumor site." (PMID 32508809, 2020). "Consistently, IL-8 neutralisation antibody and CXCR2 inhibitor significantly inhibited neutrophils migration towards tumour conditional medium." (PMID 32778818, 2020). "The mobilization of neutrophils from the circulation toward the tumor is controlled by the C-X-C motif chemokine receptor 2 (CXCR2) axis." (PMID 32411122, 2020). "Collectively, our findings suggest FMNL1 works with HDAC1 to induce the expression of CXCR2 to promote tumor metastasis." (PMID 33324547, 2020). "CXCL1, CXCL2, and CXCL5 have been shown to recruit MDSCs to the pre-metastatic niche through the interaction with CXCR2; once in the pre-metastatic site, MDSCs favor tumor cell recruitment and seeding by secreting TNFα, TGFβ, IL-6, CCL2 and CXCL2." (PMID 32823961, 2020). "In the early stages of tumorigenesis, chemokines such as the CXCL1/CXCR2 axis can mediate OIS through NF-κB signalling to restrict tumor growth." (PMID 31991604, 2020). "Binding of these chemokines to tumor cell-expressed CXCR2, which was sustained by the hypoxic TME created by IL-33, resulted in tumor cell apoptosis." (PMID 33329534, 2020). "The CXCR2 pathway has a major role in the control of neutrophil recruitment into tumours, and antagonists of the CXCR2 receptor have reduced tumour growth in murine studies." (PMID 32887739, 2020). "In vivo, administration of a CXCR1/2-targeted pepducin (x1/2pal-i3), or CXCR2-specific antagonist (AZD5069), in combination with IR to PTEN-deficient xenografts attenuated tumour growth and progression compared to control or IR alone." (PMID 32743555, 2020). "With this aim, several groups have explored the generation of synthetic TILs expressing chemokine receptors for different chemokines secreted by tumor cells, such as CXCR2, which is the receptor for several chemokines such as CXCL1 and CXCL8." (PMID 33680923, 2020). "They further showed that anti-CXCR2 monoclonal antibody therapy led to significant anti-tumor activity, even after delayed anti-PD1 treatment." (PMID 33256070, 2020). "Targeting CCR2+ TAM and CXCR2+ TAN in combination caused influx of both CD8+ and CD4+ T cells in the tumor microenvironment, improving antitumor immunity and reducing tumor burden." (PMID 31297636, 2020). "Further, we demonstrate that neutrophils incubated under a tumor-mimicking in vitro environment show a high cell surface expression of C-X-C motif chemokine receptor 2 (CXCR2) and secrete high levels of interleukin (IL)-8." (PMID 32411122, 2020). "CXCR2+ PMN-MDSCs enhance tumor growth, whereas their migration from the periphery to the tumor appears to be dependent on CXCR2." (PMID 32488850, 2020).
tumor (continued). "Integrin αvβ6-CAR T cells modified to express CXCR2 migrate more efficiently towards tumor-produced IL-8." (PMID 32423475, 2020). "In the same study, the resistance to docetaxel was reversed by treatment of an antagonist for CXCR2 performing as the inhibition of tumor growth and potentiation of chemotherapy-induced senescence." (PMID 32508809, 2020). "Tumor cells capable of releasing CXCL2 ligand activate CXCR2+ TAMs, enhancing their suppressive effect on T cells and pro-angiogenic activity, with consequent tumor growth." (PMID 32488850, 2020). "Both U-87MG and GB primary cultures were found responsive to CXCL8 in cell chemotaxis and migration assay, thus confirming the functionality of the CXCL8-CXCR1/CXCR2 axis and its potential role in modulating tumour invasiveness." (PMID 31986121, 2020). "Antagonists of CXC receptors, specifically dual antagonists of CXCR1 and CXCR2, have the potential to interfere with tumor-orchestrated recruitment of neutrophils/MDSCs into the TME." (PMID 32244751, 2020). "Although CCR2 inhibitors show promise in depleting TAMS in vivo in patients, a compensatory mechanism of CXCR2+ neutrophils frustrates anti-tumor efficacy." (PMID 33304355, 2020). "The co-blockage of CXCR2 and PD-1 prevented MDSCs trafficking to the tumor, restored the anti-tumor effects of delayed ICIs treatment." (PMID 32508809, 2020). "In mouse models the potential relevance of these findings to tumor progression was supported by the fact that the expression of CXCR2 and p-Akt was coordinated with PD-L1 expression in the tumors, and by immune-suppressive activities of the CAFs." (PMID 32582148, 2020). "The CXCR2 ligands (CXCL1, -2 and -5) recruit CXCR2+ neutrophils into the tumor microenvironment, which interact with cancer cells and induce expression of metastasis-involved genes such as CXCR4 and MMP-2." (PMID 33096815, 2020). "In a PDAC mouse model, genetic ablation of CXCR2 abrogated metastasis while pharmacological inhibition of CXCR2 decreased tumor growth." (PMID 32509781, 2020). "Studies on animal models indicated that transfer of T cells genetically modified to express CXCR2 enhanced their homing to the tumour site and improved anti-tumour immune response." (PMID 32183246, 2020). "Along these lines, a study by Massagués and colleagues demonstrated that CXCR2 inhibitors that were administered to mice prior and in the course of chemotherapy, sensitized the tumor cells to the cytotoxic effects of the drugs." (PMID 32582148, 2020). "Expression of CXCR2, CD11b (a marker of granulocytes) and CD66b (a marker of neutrophils) was analyzed by immunohistochemistry on tumor samples." (PMID 32727083, 2020). "Blockade of CXCR2 signalling reduces tumour growth rate, accompanied by a decreasing amount of TANs and increasing activity of CD8+ T cells." (PMID 32778818, 2020). "CXCR2 can be expressed in microvascular endothelial cells, and in tumor vessels in several types of human cancer." (PMID 31690961, 2020). "For instance, BC cell-released TNF-α stimulates BM-MSCs to secrete CXCR2 (C-X-C Motif Chemokine Receptor 2) ligands which, in turn, recruit CXCR2 + neutrophils into the tumor, thus promoting metastases." (PMID 32850459, 2020). "The pronounced effect of targeting CXCR1 and CXCR2 signalling observed in our in vivo models is consistent with the multifactorial role of chemokines within the tumour microenvironment." (PMID 32743555, 2020). "The present study evaluated the diagnostic significance of selected receptors for chemokines (CXCR4 and CXCR2) in comparison to the well-established tumor marker–CEA." (PMID 32867211, 2020). "It is worth noting that combined treatment with CCR2 inhibitors and CXCR2 inhibitors can overcome this compensatory effect, and augment anti-tumor immunity and improve response to FOLFIRINOX chemotherapy, prolonging the survival of PDAC mice." (PMID 33224886, 2020).
tumor (continued). "CXCR1 and CXCR2 inhibitors show encouraging results in tumor preclinical models when they are used in combination with chemotherapy and checkpoint inhibitors and are now in use in several clinical trials." (PMID 32733442, 2020). "In cancer, the CXCR2 axis is the primary player for neutrophil recruitment to the tumor sites combined with G-CSF." (PMID 32630815, 2020). "By activating CXCR2, CXCL1 is associated with cancer cell growth and proliferation, tumor angiogenesis and metastasis." (PMID 32326946, 2020). "To gain further insight on the molecular mechanism mediating gMDSC recruitment to BCM-2277 tumors, we then treated a cohort of tumor-bearing mice with an inhibitor of CXCR2, the receptor through which CXCL1 and CXCL2 signal." (PMID 32634121, 2020). "IL-33-activated ILC2s sustain CXCR2 expression on tumor cells by producing high amounts of CXCR2 ligands, which, in turn, induce apoptosis in malignant cells." (PMID 33138017, 2020). "Their receptor CXCR2 was specifically expressed in G-MDSC purified from RET.AAD tumor with spontaneous melanoma." (PMID 32443699, 2020). "Behavioral results further demonstrated that CXCR2 antagonist attenuated BCP hypersensitivity after tumor cell inoculation in a dose-dependent manner, suggesting that enhanced neuronal CXCR2 also occurs in the supraspinal pain modulatory circuitry." (PMID 30606213, 2019). "In contrast, treatment with a clinically relevant small molecule inhibitor of CXCR2 in KPC mice not only reduced tumor metastasis but also prolonged mice survival with the combination of CXCR2 inhibitor and gemcitabine or anti-PD-1 immunotherapy." (PMID 31652904, 2019). "The biological effects of IL-8 are mediated through the binding of IL-8 to two cell-surface receptors, the GPCRs CXCR1 (IL-8RA) and CXCR2 (IL-8RB), which are present in various types of normal as well as tumor cells." (PMID 31191652, 2019). "Next, we sought to determine if MDSCs express the IL-8 receptors CXCR1 and CXCR2, and if MDSCs are attracted to the tumor by IL-8." (PMID 31781510, 2019). "We observed reduced luciferase expression in hind limbs and the forelimbs of Cxcr2−/− mice than those of wild type mice, suggesting that host Cxcr2 plays a crucial role in directing tumor cells toward bones." (PMID 30871004, 2019). "The relative level of hematopoiesis gene (e.g., Hoxa5, Hoxa7, Evi1, and Meis124,25) mRNA expression was decreased in CXCR2−/− tumor-bearing mice." (PMID 31395859, 2019). "Similar results supporting a tumor-promoting angiogenic role for CXCR2 were also reported for pancreatic ductal adenocarcinoma and ovarian cancer." (PMID 30800123, 2019). "In summary, this work suggested a RelA/CXCL1/CXCR2 axis as a major guardian against PDAC tumor development." (PMID 31561620, 2019). "The inhibition of CXCR2 also enhances the sensitivity to anti-programmed death 1 therapy, which reinforces the endogenous anti-tumor immune response." (PMID 31788042, 2019). "In KPC pancreatic carcinoma and inflammation-driven and spontaneous intestinal adenocarcinoma, the migration of myeloid cells, especially neutrophils, to the tumor microenvironment is impaired when CXCR2 signaling is suppressed." (PMID 31474975, 2019). "Various solid tumors, including RCC, secrete ligands for the chemokine receptor CXCR2 to promote angiogenesis, tumor growth and metastasis." (PMID 30805309, 2019). "In particular, the sensitivity of metastases to neutrophil inhibition holds promise as a potential treatment option for stage II/III CRC patients with undergoing primary tumor resection before treatment with CXCR2 or ALK5 inhibitors." (PMID 31526760, 2019). "Other than a classical chemokine receptor, we found a novel function of CXCR2 in regulating the differentiation of hematopoietic progenitor cells under tumor conditions." (PMID 31395859, 2019).
tumor (continued). "A20-28z CXCR2 T-cells demonstrate superior anti-tumor activity in vivo against αvβ6-expressing tumor xenografts and, although the CAR also engages the mouse ortholog of αvβ6, therapy was well tolerated." (PMID 31091832, 2019). "The increased binds of CXCL1 or CXCL2 to CXCR2 leads to reduced SAP18 expression under tumor conditions, which subsequently activates the ERK/STAT3 signaling pathway to promote mo-MDSCs accumulation." (PMID 31395859, 2019). "Subsequent to this, the high production of reactive oxygen species (ROS) elicits the expression of chemokine (C-X-C motif) receptor 2 (CXCR2) on tumor cells." (PMID 31354745, 2019). "The inhibition of CXCR2 or downstream pathways can decrease the number and activity of CSCs in vitro and in xenografts, and increase the efficacy of docetaxel to decrease tumor volume." (PMID 31788042, 2019). "There was a significant tumor shrinkage in the tumor with the use of anti-PD1 in mice reconstituted with CXCR-2 (-/-) hematopoietic cells when compared to wild type mice." (PMID 35582715, 2019). "In order to evaluate the therapeutic activity of A20-28z CXCR2+ T-cells in vivo, three tumor xenograft models were established that co-express αvβ6 and IL-8." (PMID 31091832, 2019). "T-cells do not express the IL-8-responsive chemokine receptors, CXCR1 or CXCR2, and consequently they are unable to respond naturally to a tumor-derived gradient of IL-8." (PMID 31091832, 2019). "In the tumor microenvironment, breast cancer growth in both autocrine and paracrine manners are regulated by CXCR2 and its ligands produced by stromal cells." (PMID 31788042, 2019). "CXCR2 + PMN-MDSCs are critical for the decrease of anti-PD1 antibody activity, and anti-CXCR2 synergized with anti-PD1 in reducing tumor weight in an in vivo model." (PMID 31462894, 2019). "Along the same line, pharmacological antagonist of chemokine receptors (i.e., S-265610, CXCR2-specific antagonist) were able to drastically reduce M-MDSC in tumor-bearing mice." (PMID 31447834, 2019). "To evaluate the importance of tumor-derived CXCR2 in tumor-induced osteolysis, we implanted Cl66-shCXCR2 and Cl66-Control cells on the calvaria of mice." (PMID 30871004, 2019). "In gastric cancer, LECs upregulated expression of CXCL1, which in turn increased tumor cell invasiveness via CXCR2 and stimulated lymphangiogenesis." (PMID 31105685, 2019). "Myeloid-derived suppressor cells (MDSCs) comprise a critical component of the tumor environment and CXCR2 reportedly plays a key role in the pathophysiology of various inflammatory diseases." (PMID 31395859, 2019). "Previous studies have demonstrated the knockout of the CXCR2 gene in host cells to inhibit tumor growth and increased tumor cell apoptosis." (PMID 31788042, 2019). "The results showed that the number of lung metastatic nodules was substantially reduced in CXCR2-/- tumor-bearing mice." (PMID 31395859, 2019). "While both IL-8 receptors, CXCR1 and CXCR2, can regulate tumor cell proliferation and metastasis in a variety of cancers, signaling via CXCR2 appears to have a more pronounced effect." (PMID 31227783, 2019). "IL-33 promotes ILC2 secretion of CXCR2 ligands that bind to CXCR2-expressing tumor cells, reinforcing tumor cell-specific apoptosis independent of adaptive immunity." (PMID 32117199, 2019). "The anti-tumor effect of targeting CXCR2 was reflected in both in vitro and in vivo models of breast cancer, and further supports the development of CXCR2 inhibitors as a clinical therapy in breast cancer." (PMID 31788042, 2019). "In our model, tumor-infiltrated cytotoxic CD8+ T cells decreased in heterozygous Cxcr2 knockout PKF2h mice." (PMID 30659170, 2019). "Other scientific groups also report that CXCR2 expression by the tumor cells promotes tumor cell invasion and metastasis formation." (PMID 30871004, 2019). "The results showed that the expression of CXCR2 on lineage−CD45+ Ly6G− bone marrow cells increased with the extension of tumor-bearing time." (PMID 31395859, 2019).